ENSG00000268649 (novel transcript)
Gene: Long non-coding RNA gene on chromosome 20 (58,817,132 to 58,817,725, reverse strand). Ensembl gene ENSG00000268649.
Gene Ontology:
Biological process: miRNA-mediated post-transcriptional gene silencing
Cellular component: RISC complex